RARRES2 (retinoic acid receptor responder 2)
Diseases named in the same sentence as RARRES2 in open-access papers (continued):
Sharing a sentence is not in itself a finding about the gene and the disease.
atherosclerosis (3 papers, 2023 to 2024). A disease characterized by the build-up of fatty material and calcium deposition in the arterial wall resulting in partial or complete occlusion of the arterial lumen. "We have identified seven genes (CHI3L1, CD36, LEPR, RETN, IL-18, RBP-4, and RARRES2) that may be associated with IR and atherosclerosis as having possible evidence based on the disease pathogenesis of ED and inflammation." (PMID 36984867, 2023). "In short, this RARRES2 SNP might be the marker associated with IR and atherosclerosis." (PMID 36984867, 2023). "CHI3L1, CD36, IL-18, and RARRES2 genes have also been reported to be associated with IR, whereas APOA1, CD36, LEP, FN1, and CETP genes were found to be associated with atherosclerosis." (PMID 36984867, 2023). "This review identified CHI3L1, CD36, LEPR, RETN, IL-18, RBP-4, and RARRES2 genes as the potential genetic markers of IR and atherosclerosis in T2DM patients with CAD." (PMID 36984867, 2023). "This review focuses on the link between IR, T2DM, atherosclerosis, CAD, and the potential genetic markers CHI3L1, CD36, LEPR, RETN, IL-18, RBP-4, and RARRES2 genes." (PMID 36984867, 2023).
glioblastoma (3 papers, 2022 to 2023). The most malignant astrocytic tumor (WHO grade IV). "The significant correlation between the ACS signature enrichment and the number of TAMs is of particular interest given the up-regulation of RARRES2 in BE-GICs and the role of TAMs in glioblastoma invasion." (PMID 36412091, 2022). "In vitro experiments were conducted to demonstrate that targeting RARRES2 inhibits glioblastoma progression and macrophage infiltration, particularly IDH wild-type GBM." (PMID 37246211, 2023).
glioma (3 papers, 2023 to 2026). A benign or malignant brain and spinal cord tumor that arises from glial cells (astrocytes, oligodendrocytes, ependymal cells). "In both glioma and pan-cancer contexts, RARRES2 expression is significantly positively correlated with the infiltration of M2-like macrophages, NK cells, and CD8+ T cells." (PMID 42247404, 2026). "Given that RARRES2 receptors are predominantly found in myeloid and glioma cells, we hypothesize that RARRES2 may regulate tumor progression through autocrine pathways and influence macrophage recruitment and differentiation via paracrine pathways." (PMID 42247404, 2026).
adrenocortical tumors (2 papers, 2023 to 2024). "RARRES2 is a small, secreted protein associated with a variety of cancers, and higher serum RARRES2 levels have been shown to be associated with improved overall survival in adrenocortical tumors (P = 0.0227)." (PMID 36968845, 2023). "Within the AME, we detected a high expression of RARRES2, a key modulator of tumour growth and inflammation, in line with a previous study reporting a higher RARRES2 expression in benign compared to malignant adrenocortical tumours." (PMID 39167619, 2024).
breast tumor (2 papers, 2023 to 2025). "A single-cell transcriptomic study found that RARRES2 (Retinoic Acid Receptor Responder 2) is the most downregulated gene in brain-metastatic TNBC tumors compared to primary breast tumors." (PMID 40427160, 2025). "To further investigate the expression of RARRES2 in different tumor sites, we analyzed another separate patient cohort comprising unmatched primary breast tumors and brain metastasized lesions." (PMID 37491281, 2023). "The expression of RARRES2 was examined in this cohort, revealing a significantly lower level of RARRES2 expression in BrM compared to matched primary breast tumor samples (P < 0.0001)." (PMID 37491281, 2023). "Herein, we for the first time identified RARRES2 as the most significantly downregulated gene in BCBrM compared with primary breast tumors." (PMID 37491281, 2023). "In this cohort, RARRES2 expression was found to be significantly decreased in BCBrM compared with primary breast tumors, and moreover, with primary brain tumors (GSE100534) (P = 0.0016, P = 0.0003)." (PMID 37491281, 2023). "The results demonstrated a notable decrease in RARRES2 expression in BrM samples when compared to primary breast tumors." (PMID 37491281, 2023). "Furthermore, when analyzing the GSE62598 dataset, we did not observe a decrease in RARRES2 expression in liver, bone, or lung metastases compared to primary breast tumors." (PMID 37491281, 2023).
chordoma (2 papers, 2014 to 2021). Chordomas are rare malignant tumors arising from embryonic remnants of the notochord in axial skeleton. "In addition, RARRES2 is identified as a potential biomarker for chordoma which is a rare, low-malignant bone tumor." (PMID 34256750, 2021). "We demonstrate the expression of new potential candidates for chordoma tumorigenesis, such as CD24, ECRG4, RARRES2, IGFBP2, RAP1, HAI2, RAB38, osteopontin, GalNAc-T3, VAMP8 and others." (PMID 24452533, 2014).
hepatocellular carcinoma (2 papers, 2018 to 2021). A malignant tumor that arises from hepatocytes. "Reduced expression of RARRES2 is observed in human hepatocellular carcinoma." (PMID 34256750, 2021).
allergic asthma (1 paper, 2023). A asthma with a basis in a pathological type I hypersensitivity reaction. "Although there are no available data referring to the changes in RARRES2 expression in peripheral blood cells, or the molecular mechanism of chemerin activity in relation to AD, a protective role of the chemokine in other allergic diseases, such as allergic asthma, has been documented." (PMID 37511372, 2023).
asthma (1 paper, 2016). "In addition, miR-708 also caused downregulation of expression of several ‘asthma-related’ genes such as CD44, ADAM33 and RARRES2." (PMID 26998837, 2016). "In addition, expression of RARRES2, CD44 and ADAM33, genes known to contribute to the pathophysiology of asthma, were found to be inhibited in miR-708-transfected cells." (PMID 26998837, 2016).
astrocytic tumor (1 paper, 2022). A glial tumor of the brain or spinal cord showing astrocytic differentiation. "EGFR is the most frequently amplified oncogene in astrocytic tumors; expression of genes SRI, NPTX2, MEST, RARRES2, and SEPTIN7 in association with GBM is reported in this study." (PMID 35327982, 2022).
B-cell lymphoma (1 paper, 2022). "Interestingly, some of these genes, such as LEP, ALOX12, RARRES2, DLEU7, and FOXR1, have been reported to be associated with other hematologic malignancies, including AML, chronic lymphocytic leukemia (CLL), and B-cell lymphoma." (PMID 35847864, 2022).
bone metastasis (1 paper, 2021). Transfer of a neoplasm from its primary site to bones. "In this study, LOC285972 was found to be down-regulated in both two groups and cis-regulate RARRES2 in the group of bone metastasis vs lung metastasis." (PMID 34256750, 2021).
choriocarcinoma (1 paper, 2019). An aggressive malignant tumor arising from trophoblastic cells. "In line with its proposed tumor suppressor function, RARRES1, along with RARRES2, was reduced in choriocarcinoma and its expression was also significantly reduced in certain choriocarcinoma cell lines (i.e., Jeg-3 and BeWo)." (PMID 31905805, 2019).
Cognitive impairment (1 paper, 2024). Abnormal cognition is characterized by deficits in thinking, reasoning, or remembering. "In summary, this study innovatively examined the roles of ferroptosis and Rarres2 in chronic noise-induced cognitive impairment." (PMID 39343514, 2024). "Furthermore, Mendelian randomization (MR) analysis was employed to analyze the relationship between ferroptosis-related genes (retinoic acid receptor responder 2, Rarres2) and cognitive impairment." (PMID 39343514, 2024).
cyst (1 paper, 2025). A sac-like closed membranous structure that may be empty or contain fluid or amorphous material. "RARRES2 (retinoic acid receptor responder protein 2, also known as chemerin) is a chemoattractant implicated in inflammation and adipogenesis, both of which may affect cyst development and fibrosis." (PMID 40681500, 2025).
dermatitis (1 paper, 2013). An inflammatory process affecting the skin. "Most notably, several RAR target genes involved in retinoid signaling were induced in allergen-induced dermatitis, whereas expression of RAR targets which are not implicated in retinoid signaling (Krt4, Rarres2, Tgm2) was not significantly altered." (PMID 23977003, 2013).
diabetic kidney disease (1 paper, 2024). Progressive kidney disorder caused by vascular damage to the glomerular capillaries, in patients with diabetes mellitus. "For example, variants in the RARRES2 gene are associated with serum chemerin levels and increase the risk of diabetic kidney disease in type 2 diabetes mellitus." (PMID 39595602, 2024).
endometritis (1 paper, 2020). An acute or chronic, usually bacterial infectious process affecting the endometrium. "Therefore, ADIPOQ and RARRES2 represent suitable biomarkers able to provide an early diagnosis of subclinical endometritis and predict the risk of persistence of uterine inflammation." (PMID 32567551, 2020). "In contrast, plasma RARRES2 at 21 DPP (AUC = 0.423; P = 0.443) and at 45 DPP (AUC = 0.738; P = 0.017) showed either no ability or a low ability to discriminate cows with cytological endometritis." (PMID 32567551, 2020). "However, unlike ADIPOQ, RARRES2 ROC curve and OR analysis revealed that only uterine fluid RARRES2 concentrations were suitable to discriminate persistent endometritis cows at 45 DPP." (PMID 32567551, 2020).
epilepsy (1 paper, 2023). A brain disorder characterized by episodes of abnormally increased neuronal discharge resulting in transient episodes of sensory or motor neurological dysfunction, or psychic dysfunction. "The MR analyses also implicated FLRT2 and RARRES2 in epilepsy." (PMID 36504281, 2023). "We also observed two protein‐pQTL pairs (FLRT2‐rs17646457 and RARRES2‐rs3735172) with shared effects with focal epilepsy, as well as hippocampal sclerosis‐related epilepsy." (PMID 36504281, 2023).
esophageal cancer (1 paper, 2022). A primary or metastatic malignant neoplasm involving the esophagus. "The RARRES2–CMKLR1 axis has been described to induce the migration of MSCs to esophageal cancer." (PMID 35723360, 2022).
Ewing sarcoma (1 paper, 2018). A small round cell tumor that lacks morphologic, immunohistochemical, and electron microscopic evidence of neuroectodermal differentiation. "[As an aside, in Ewing sarcoma, a rare, malignant tumor that grows inside the bones and in nearby soft tissues, RARRES2 showed a high rate of methylation and was one of only eight genes to have a frequency of silencing >20%." (PMID 30555465, 2018).
Headache (1 paper, 2025). Cephalgia, or pain sensed in various parts of the head, not confined to the area of distribution of any nerve. "Genetically, CD302 was associated with headache (P = 2.60 × 10−5), RARRES2 was associated with neck or shoulder pain (P = 3.94 × 10−4), TNFRSF1B was associated with back pain (P = 7.96 × 10−5), and CD74 was associated with hip pain (P = 3.21 × 10−4)." (PMID 40048323, 2025).
lung carcinoma (1 paper, 2021). "Previous studies have also shown that higher RARRES2 expression was associated with positive prognosis in lung cancer patients." (PMID 34552612, 2021).
mesothelioma (1 paper, 2018). A usually malignant and aggressive neoplasm of the mesothelium which is often associated with exposure to asbestos. "Regarding chemerin's role in mesothelioma, literature on the topic is scarce, though it was one of the first identified cancer types where RARRES2 expression was altered (significantly increased, compared to matched normal tissue)." (PMID 30555465, 2018).
morbid obesity (1 paper, 2019). An excess of body weight, normally defined as an individual with a body mass index greater than 35 or a body weight greater than one hundred percent of ideal body weight. "In biopsy specimens of the prostate, mtDNA copy number was negatively associated with the expression of the RARRES2 gene in patients with morbid obesity without T2DM." (PMID 30871547, 2019).
muscle tumors (1 paper, 2023). "In addition, 25 DPs are related to muscle tumors; 8 DPs (APOE, FCER1A, FCER2, GSK3B, HSPD1, IL6R, MMP7, and RARRES2) are linked to proliferation of muscle cells." (PMID 36918772, 2023).
osteoporosis (1 paper, 2022). A condition of reduced bone mass, with decreased cortical thickness and a decrease in the number and size of the trabeculae of cancellous bone (but normal chemical composition), resulting in increased fracture incidence. "We selected RARRES2 rs7806429 SNV, to observe its association with BMD and serum RARRES2 levels, which may further add in our understanding of the role of RARRES2 as potential biomarker for osteoporosis in postmenopausal females." (PMID 36531488, 2022). "Single nucleotide variations in RARRES2 gene were studied in relation to various diseases but not osteoporosis." (PMID 36531488, 2022).
parasite (1 paper, 2023). "Notably, the expression patterns of the Rarres2 transcript variants were unaffected by a high-fat diet or viral, bacterial, and parasite infections." (PMID 36609751, 2023).
parasitic infection (1 paper, 2023). "Our findings showed that the splicing pattern of RARRES2 mRNA was unaltered by a high-fat diet and bacterial, viral, or parasitic infection, nor by proinflammatory cytokine treatment." (PMID 36609751, 2023).
pituitary tumor (1 paper, 2025). A benign or malignant neoplasm affecting the pituitary gland. "In the pituitary tumor cohort (GSE169498), we identified a total of five MRGs (MED27, RARRES2, AKAP8L, RAB5B, and STK39) that are associated with the invasiveness of pituitary tumors." (PMID 40873641, 2025).
pleural mesothelioma (1 paper, 2025). A neoplasm that arises from the mesothelial cells of the pleura. "The expression of RARRES2 was found to be increased in mesothelioma cells compared to normal mesothelial cells, suggesting a role for chemerin in pleural mesothelioma." (PMID 40564073, 2025).
polymyositis (1 paper, 2025). A rare idiopathic inflammatory myopathy characterized by symmetric proximal muscle weakness and elevated muscle enzymes. "The upregulation of granulysin (GNLY), encoding for the cytosolic protein granulysin (expressed in cytotoxic T cells and natural killer cells, and previously associated with polymyositis, and chemerin (RARRES2), a leukocyte chemoattractant, may be related to the inflammation process." (PMID 40841884, 2025).
schizophrenia (1 paper, 2023). A major psychotic disorder characterized by abnormalities in the perception or expression of reality. "The pQTL‐protein pairs CTSS‐rs79671334 and RARRES2‐rs3735172 had shared effects with schizophrenia and year of schooling, respectively." (PMID 36504281, 2023).
skin infection (1 paper, 2023). An inflammatory process affecting the skin, caused by bacteria, viruses, parasites, or fungi. "Indeed, skin transcriptome analyses of antimicrobial peptides differentially regulated after skin infection with C. acnes or Leishmania braziliensis revealed elevated RARRES2 transcript levels." (PMID 36609751, 2023).
tumor (30 papers, 2018 to 2026). "Downregulation or loss of chemerin/RARRES2 in malignancies can modulate the tumor microenvironment and tumor immune responses and act as both a pro- and anti-inflammatory mediator compared to the normal tissue counterparts." (PMID 36313435, 2022). "Notably, genes exhibiting a positive correlation with RARRES2 were predominantly associated with tumor metastasis-related processes, including biological adhesion, cell migration and proliferation." (PMID 37491281, 2023). "RARRES2, a fat factor, is the key participant in initiating early immune responses, which facilitates the proliferation and migration of tumor cells by upregulating the PD-L1 gene." (PMID 38601538, 2024). "Although RARRES2 has different expression patterns in different tumors, RARRES2 can promote GBM mesenchymal properties by inhibiting the ubiquitin‒proteasome degradation of CMKLR1, which indicates that RARRES2 can support tumor progression in GBM." (PMID 37246211, 2023). "Previously conducted studies found that RARRES2 acts as a secreted protein that recruits CMKLR1-expressing NK cells to tumor sites to exert tumor suppressive effects indirectly." (PMID 38269250, 2023). "Chemerin/RARRES2 is commonly downregulated across several tumor types and often employed by tumor cells to escape immune clearance by tumor-infiltrating effector leukocytes." (PMID 35245208, 2022). "The chemerin gene RARRES2 showed high expression in quite a number of tumor cell lines, e.g., from the brain and pancreas." (PMID 35008289, 2021). "The fact that others observed reduced placental Rarres2 expression following more profound maternal food restriction suggests metabolic functions of the peptide beyond its potential tumor-suppressor role that need further investigation." (PMID 31905805, 2019). "RARRES2 has been shown to be downregulated in many tumor types, suggesting a mechanism of immune escape." (PMID 30400822, 2018). "Chemerin (RARRES2) is an endogenous innate leukocyte chemoattractant previously shown to recruit immune cells via its receptor CMKLR1 into the tumor microenvironment and thereby suppresses tumor growth." (PMID 30400822, 2018). "Research has shown that Rarres2 can act as a tumor suppressor gene." (PMID 39343514, 2024). "For example, the ligand of the chemerin signalling pathway, RARRES2, was primarily sent by MTCs and was mainly received by macrophages, reflecting that tumour cells may regulate the phenotype of macrophages through the secretion of RARRES2." (PMID 38318640, 2024). "The researchers concluded that RARRES-2 secreted by CAMs constituted a potential chemoattractant for MSCs and its inhibition may delay tumour progression." (PMID 39120301, 2024). "RARRES2 acts as a chemokine through recruitment and plays an important role in tumor immunity." (PMID 36895470, 2023). "Abnormal RARRES2 expression has been detected in tumor cells." (PMID 36895470, 2023). "Likewise, the genes encoding the retinoic acid receptor responder 2 (RARRES2) and G protein subunit gamma 4 (GNG4) are thought to function as tumour suppressors." (PMID 37276213, 2023). "Subsequently, after further analyzing the tumor mutational burden (TMB) in GBM, we confirmed that RARRES2 in the prognostic risk model could be used as a crucial gene signature to predict the prognosis, immune cell infiltration and IDH status of GBM patients." (PMID 37246211, 2023). "In order to test our hypothesis that forced overexpression of chemerin by tumor cells would act to recruit anti-tumor leukocytes and suppress tumor growth, we used lentiviral transduction to introduce the mouse RARRES2 gene into EMT6 tumor cells." (PMID 31139180, 2019). "Furthermore, we performed IHC to assess the expression of RARRES2 protein in human tumor samples." (PMID 37491281, 2023).